MPO (myeloperoxidase)
Diseases named in the same sentence as MPO in open-access papers (continued):
Sharing a sentence is not in itself a finding about the gene and the disease.
acute myeloid leukemia (continued). "We present a case of MPO-negative, myeloid antigen-positive acute lymphoblastic leukemia who progressed with refractory phenotypic acute myeloid leukemia while receiving lymphoid-directed therapy and discuss concerns raised by the adoption of the new, more stringent diagnostic criteria for BAL." (PMID 30140473, 2018).
Parkinson disease (28 papers, 2013 to 2025). A progressive degenerative disorder of the central nervous system characterized by loss of dopamine producing neurons in the substantia nigra and the presence of Lewy bodies in the substantia nigra and locus coeruleus. "Studies have demonstrated that MPO can activate neuroinflammatory processes, and targeting MPO reduces neuroinflammation associated with X-linked dystonia-parkinsonism." (PMID 40401059, 2025). "MPO, which is expressed by neurons in the substantia nigra pars compacta and contributes to α-synuclein pathology, has been implicated in Parkinson’s disease (PD)." (PMID 35739985, 2022). "The clinical use of these MPO inhibitors is feasible and evaluated clinically for Parkinson’s disease, multiple system atrophy and amyotrophic lateral sclerosis." (PMID 38367056, 2024). "A separate study also found that males with Parkinson’s disease had increased MPO levels within the cerebral spinal fluid (CSF) compared to females." (PMID 39456241, 2024). "The expression of MPO is increased in the brains of patients with Alzheimer’s or Parkinson’s disease, and MPO is reportedly activated in multiple sclerosis plaques." (PMID 33535986, 2021). "Ablation of MPO has been reported to alleviate features of Parkinson’s disease in mice, and resveratrol has been shown to confer protection against rotenone-induced neurotoxicity by modulating MPO levels in glial cells." (PMID 33445746, 2021). "The expression of MPO is increased in the brains of patients with Alzheimer’s or Parkinson’s disease, and MPO has been reported to be activated in human multiple sclerosis plaques." (PMID 33573686, 2021). "Activation of the immune system during systemic inflammation can induce sickness behavior and forced expression of human MPO in a murine Parkinson’s Disease model exacerbates motor impairment." (PMID 32050431, 2020). "GAPDH oxidation and aggregation has been reported in a number of diseases in which macrophages and myeloperoxidase (MPO)-derived reactive species have been observed, including Alzheimer’s, Lou Gehrig’s, Huntington’s, and Parkinson’s diseases." (PMID 39449960, 2015). "Similar regulatory effects of resveratrol on MPO levels were observed in microglia treated with MPP+, another Parkinson’s disease-linked neurotoxin, supporting the beneficial effects of resveratrol on the brain." (PMID 23593274, 2013). "Moreover, MPO+ cells (probably neutrophils) were increased in the brain in subjects with AD and Parkinson’s disease (PD), thus supporting a role for this enzyme in neurodegeneration." (PMID 36034148, 2022). "Moreover, oxidative stress (thiobarbituric acid reactive substances and advanced oxidation protein products) and inflammatory markers, such as myeloperoxidase, were significantly elevated in the blood of Parkinson’s disease patients." (PMID 33052927, 2020). "Interestingly, in a mouse model of Parkinson's disease, ablation of the myeloperoxidase gene is protective, which supports the conclusion that myeloperoxidase is a major contributor to the oxidative damage generated by pathological neuroinflammatory processes." (PMID 31428227, 2019). "Our analysis validates the interdependence of AD, dementia, and Parkinson’s disease through various common genes (i.e., A2M, ABCA7, PLAU, PSEN2, and MPO)." (PMID 38790243, 2024). "Recently, a small molecule inhibitor of MPO (AZD3241) was shown to be safe and tolerable in healthy adults and patients with Parkinson’s disease and is currently under clinical investigation for the treatment of Multiple System Atrophy." (PMID 31611761, 2019). "MPO oxidizes nonreactive nitrite whose concentration is increased in parkinsonism to reactive nitrite (NO2−) and, thus, nitrosylates many proteins." (PMID 23935251, 2013).
thrombosis (28 papers, 2016 to 2025). "In this study, we systematically investigated the correlation between NETs and hHcy-associated thrombosis by measuring key NETs markers (myeloperoxidase, MPO; citrullinated histone H3, CitH3) and cell-free DNA (cfDNA) levels." (PMID 41451132, 2025). "Elevated levels of myeloperoxidase (MPO), a member of the heme peroxidase superfamily, are associated with increased inflammation and oxidative stress, and in patients with venous thrombosis, elevated levels are often associated with poor prognosis." (PMID 39297312, 2024). "Regarding calprotectin and MPO, the risk of thrombosis increased following a logarithmic curve, with a higher slope at low values." (PMID 32781781, 2020). "This study is the first to investigate the association between NETs-associated regulatory proteins (MPO, CitH3) and cell-free DNA with thrombosis in hHcy, while developing and validating a clinically applicable prediction model for identifying high-risk patients." (PMID 41451132, 2025). "A various number of clinical studies have shown that serum MPO and DNA levels are associated with an increased risk of deep vein thrombosis and pulmonary embolism in humans suggesting that MPO levels might be used as a biomarker in patients with PV and ET." (PMID 38338695, 2024). "This study aimed to determine the role of soluble P-Selectin, Neutrophil Extracellular Traps (NET), and myeloperoxidase (MPO) in the occurrence of Deep Vein Thrombosis, particularly as risk factors in patients with malignancy receiving platinum-based chemotherapy." (PMID 39810847, 2024). "In conclusion, our study demonstrated that NETs, MPO-DNA, and CitH3 levels were notably increased in the peripheral blood of CHF patients with venous thrombosis, which showed good diagnostic value for venous thrombosis in CHF patients." (PMID 38491551, 2024). "MPO is a biomarker of neutrophil activation and is involved in the pathogenesis of immune-thrombosis." (PMID 39810847, 2024). "Clinical studies also have demonstrated significant changes in the levels of serum or plasma NETs biomarkers, such as citrullinated histones, myeloperoxidase, neutrophil elastase, nucleosomes, DNA, and their complexes in patients with thrombosis." (PMID 36224604, 2022). "Extracellular DNA was in close proximity to neutrophils, together with positive staining of MPO, NE, and histones by immunostaining assay after induction of venous thrombosis." (PMID 36224604, 2022). "Furthermore, elevated concentrations of MPO and MRP have been linked to a higher risk of cardiovascular diseases, such as thrombosis." (PMID 40066452, 2025). "The autopsy results showed that a higher level of MPO was detected in the criminal plaque erosion site, and the whole body MPO concentration was also higher in the patients with criminal plaque erosion, indicating that MPO may be related to thrombosis and PE." (PMID 35419382, 2022). "Besides, the levels of plasma DNA and calprotectin were higher in patients with splanchnic vein thrombosis (SVT) than those with DVT, whereas the level of MPO was much higher in patients with DVT of the lower limbs than those with SVT." (PMID 36224604, 2022). "In an in vivo model, we found that GSCs expressing SCEL augment venous thrombosis with higher level of IL8 concentration and MPO–DNA complexes in plasma." (PMID 33414368, 2021). "As biomarkers of NETs, myeloperoxidase (MPO) and cell-free DNA (cfDNA) expression have been examined in lymphomas with or without thrombosis." (PMID 40076681, 2025). "MPO was elevated in DLBCL patients without thrombosis, while cfDNA was elevated in DLBCL patients with thrombosis." (PMID 40076681, 2025). "A recent study demonstrated elevated plasma levels of myeloperoxidase–DNA complexes in patients with arterial as well as with venous thrombosis, although an increased level was not predictive of future cardiovascular events or death." (PMID 39519000, 2024).
thrombosis (continued). "This study found that the concentration of NETs, MPO-DNA, and CitH3 in the VTE group was higher than that in the non-VTE group, suggesting that NETs were expressed highly in the peripheral blood of CHF patients with venous thrombosis." (PMID 38491551, 2024). "The level of plasma MPO-DNA was higher in myeloproliferative neoplasms (MPNs) patients with a history of arterial and venous thrombosis than those without." (PMID 36224604, 2022). "The levels of TAT, H3Cit-DNA and MPO-DNA were not significantly different in patients who developed venous thrombosis in liver vessels or in any vessels as compared to those without thrombus development (data not shown for TAT)." (PMID 34504150, 2021). "Importantly, MPO-DNA levels were higher in MPN patients with previous thrombosis, especially with splenic thrombosis, positioning itself as a biomarker of thrombosis in patients with MPN." (PMID 33498945, 2021). "Levels of MPO-DNA and H3Cit-DNA were similar in patients with or without history of thrombosis, or thrombus formation during follow-up." (PMID 34504150, 2021). "But such an association was not confirmed by a prospective cohort study, which demonstrated that the baseline level of plasma MPO-DNA could not predict the development of thrombosis." (PMID 36224604, 2022).
eosinophilia (27 papers, 2014 to 2026). "When examining the published case series, prognosis was typically worse when PF was associated with MPO-ANCA positivity especially when eosinophilia was present." (PMID 26266064, 2015). "Pericardial effusion can rarely represent the initial presentation of MPO-positive AAV with eosinophilia." (PMID 41306180, 2025). "Laboratory findings include severe eosinophilia, elevated inflammatory markers, and elevated myeloperoxidase (MPO) antibodies." (PMID 40573879, 2025). "In research setting, the diagnosis of eosinophilic CRSwNP is either based directly on tissue eosinophilia (>5 eosinophils/high power field or indirectly on ECP/myeloperoxidase (MPO) ratio (>1) determined on nasal biopsies." (PMID 28706720, 2017). "Collectively, these findings established a diagnosis of MPO-positive AAV with eosinophilia." (PMID 41306180, 2025). "The diagnosis of MPO-positive AAV with eosinophilia was established." (PMID 41306180, 2025). "Physical examination was unremarkable with blood sampling revealing a marked eosinophilia (eosinophil count 17.3×109/L) and a perinuclear antineutrophil cytoplasmic antibody staining pattern on indirect immunofluorescence microscopy (myeloperoxidase antibodies 83 IU/mL)." (PMID 27899427, 2017). "After six months of mepolizumab, the patient had normalization of his peripheral eosinophilia, C-ANCA, MPO, and inflammatory markers, and was able to taper off prednisone without recurrent orbital inflammation." (PMID 40438859, 2025). "Secondary causes were excluded; bone marrow showed reactive eosinophilia and ANCA (indirect immunofluorescence and ELISA for MPO/PR3) remained negative." (PMID 41624843, 2026). "The absence of these features, coupled with high MPO-ANCA titers, favored MPO-positive AAV with eosinophilia rather than classical EGPA." (PMID 41306180, 2025). "The strongly positive MPO-ANCA and marked eosinophilia further supported a systemic vasculitic process rather than metabolic neuropathy alone." (PMID 41480456, 2025).
periodontal disease (27 papers, 2009 to 2025). "The objective of this study was to determine MPO activity in saliva and its association with severity of periodontal diseases among Thai patients." (PMID 27274868, 2016). "We report our study on the salivary MPO activity and its association with severity of periodontal diseases among Thai patients." (PMID 27274868, 2016). "Thus salivary MPO activity may be used as a risk indicator for periodontal diseases based on a simple screening method at least to raise awareness of deteriorating oral health, especially in the remote areas." (PMID 27274868, 2016). "The developed microfluidic paper-based analytical device demonstrated potential in identifying myeloperoxidase levels in saliva samples, with a limited discriminatory capacity to distinguish between healthy patients and those with periodontal disease." (PMID 40710166, 2025). "Matrix metalloproteinase‐8 (MMP‐8) and myeloperoxidase (MPO) are key biomarkers involved in the inflammatory cascade of periodontal disease." (PMID 38852177, 2025). "Our findings demonstrate the feasibility of using printed screen graphene electrodes for the sensitive and selective detection of MPO, offering a promising approach for early diagnosis and monitoring of periodontal disease." (PMID 39954018, 2025). "Both the group with periodontal disease and the healthy group, when compared to each other, showed similarity for all chromophores with regard to MPO concentrations." (PMID 40710166, 2025). "In conclusion, our results highlight the potential of MPO as a robust biomarker for periodontal disease and highlight the utility of electrochemical sensing coupled with PCA analysis for sensitive and specific detection in clinical settings." (PMID 39954018, 2025). "In summary, the results showed that, both the group with periodontal disease and the healthy group, when compared to each other, showed similarity for all chromophores with regard to MPO concentrations." (PMID 40710166, 2025). "In an experimental periodontal disease model, gliclazide treatment reduced myeloperoxidase activity, MDA, IL-1β and TNF-α levels via downregulation of PI3K and AKT (Araújo and Morais, 2019)." (PMID 34227646, 2021). "DDS displayed myeloperoxidase inhibitor activity in saliva from subjects with periodontal disease in the sandwich test disk." (PMID 32824985, 2020). "Saliva MPO activity can predict the severity of periodontal disease since is considered a gingivitis marker in patients." (PMID 30709023, 2019). "This study evaluated the effects of diode laser application in addition to SRP on inflammation and MPO, which was demonstrated by the local findings of oxidative stress, typical of periodontal disease." (PMID 30020350, 2018). "Our findings are consistent with previous studies reporting increased MPO activity in periodontal disease patients." (PMID 27274868, 2016). "MPO is an activating cytotoxic enzyme that is released from PMNs, levels of which increase in periodontal diseases." (PMID 27110759, 2016). "Increased MPO activity in gingival crevicular fluid (GCF) from patients with periodontal diseases has been reported." (PMID 27274868, 2016). "Recently, it is shown that crevicular myeloperoxidase concentrations are highly correlated with periodontal disease severity." (PMID 27897256, 2016). "Our results demonstrated significantly positive correlations between salivary MPO activity and clinical parameters of periodontal diseases." (PMID 27274868, 2016). "MPO is associated with CVD and elevated salivary MPO levels have been demonstrated in periodontal disease." (PMID 26132583, 2015). "The objective of the current study was to investigate salivary MMP-8, -9, TIMP-1 and MPO levels in relation to MI and periodontal disease." (PMID 26132583, 2015).
periodontal disease (continued). "MMP9/NGAL complex was revealed in GCF of patients with periodontal disease and accumulation of bacterial plaque as having a stronger expression and correlation with myeloperoxidase (MPO) than 92 and 82 kDa forms of MMP9." (PMID 24967433, 2014). "MPO activity in the group with periodontal disease was significantly increased compared to the control group (p<0.05)." (PMID 23843954, 2013). "The myeloperoxidase (MPO) activity in each group with periodontal disease (L) was significantly increased in comparison with the control group (NL; p<0.01)." (PMID 24130702, 2013). "The MPO activity in rats presenting with periodontal disease was significantly increased compared to control animals (p<0.001)." (PMID 23843954, 2013). "The study aimed to evaluate the suitability of myeloperoxidase (MPO) content as a local indicator of chronic inflammation, using the periodontal disease model." (PMID 20069116, 2009). "However, this study is the first to focus on evaluating the correlation between periodontal disease and salivary diagnosis by paper-based devices using MPO as a molecular biomarker." (PMID 40710166, 2025). "Previous articles have already determined that MPO activity in the saliva may reflect the severity of periodontal disease." (PMID 40710166, 2025). "Using immune–histochemical staining, periodontal myeloperoxidase expression levels, a marker of inflammation and the most abundant protein in neutrophils that is known to participate in the initiation and progression of periodontal disease, were evaluated." (PMID 39851590, 2024). "Taken together, these findings suggest that MPO activity reflects a response to inflammation in periodontal diseases and may be used as an early warning examination tool rather than a definitive diagnostic tool." (PMID 27274868, 2016). "Furthermore, the model presented may elucidate important CHD biomarkers which should be measured in patients with periodontal disease to more adequately screen for CHD risk, namely HOMA, TNF-α, CRP, IL-6, GDF-15, OPG, MPO and fibrinogen." (PMID 27846870, 2016). "Even though the statistical significance was not reached, high MPO activity may indicate the risk of periodontal diseases (OR = 1257.68, 95% CI = 0.96 to >999, p = 0.051)." (PMID 27274868, 2016). "In the present study, the objective was to develop a microfluidic paper-based analytical device (μPAD) that identifies myeloperoxidase (MPO) levels in the saliva of health patients and those with periodontal disease." (PMID 40710166, 2025). "Thus, myeloperoxidase staining in maxilla sections isolated from both rat strains was evaluated, since myeloperoxidase is an established marker of inflammation and the most abundant protein in neutrophils that is known to participate in the initiation and progression of periodontal disease." (PMID 39851590, 2024). "Currently, divergent results regarding the correlation between clinical parameters and GCF levels of MPO, BGD, and NE in periodontal disease are available." (PMID 34360367, 2021). "According to one study, AUC had the largest values for MMP-8, myeloperoxidase and MMP-9 in subjects with periodontal disease, the sensitivity to diagnosis being similar to the results obtained in the present study." (PMID 34829612, 2021). "Several studies reported the correlation of periodontal diseases and some biomarkers including IFN-γ, IL-10, IL-17, IL-1beta, lactoferrin, and myeloperoxidase (MPO)." (PMID 27274868, 2016). "Treatment with Carvedilol (10 mg/kg) significantly reduced MPO activity (p<0.05), however, GSH levels were unaltered when compared to GSH levels in rats presenting with periodontal disease and treated with vehicle." (PMID 23843954, 2013). "Therefore, this study aims to develop a microfluidic paper-based analytical device (μPAD) that identifies myeloperoxidase (MPO) levels in the saliva of healthy patients and those with periodontal disease." (PMID 40710166, 2025).
periodontal disease (continued). "The decrease in MPO activity observed in bruxistic patients after NO training at session-1 is not attributable to early stages of periodontal disease or gingivitis." (PMID 30709023, 2019). "The diabetic with periodontal disease has a lower activity of the prooxidative enzyme myeloperoxidase in the gingival crevicular fluid, compared to nondiabetics." (PMID 25525432, 2014). "MPO, by activating MMPs oxidatively in inflamed periodontal tissues, could lead to the upregulation of the MMP-dependent proteolytic cascades and participate in the progression of periodontal disease." (PMID 30669541, 2019).